CASP4LP (caspase 4 like, pseudogene)
Synonyms: formerly CASP17P
Gene: Transcribed unprocessed pseudogene on chromosome 11 (104,903,453 to 104,909,915, reverse strand). Ensembl gene ENSG00000235505.
Diseases named in the same sentence as CASP4LP in open-access papers:
CASP4LP is named in the same sentence as 1 disease in open-access papers, as found by Europe PMC text mining. Sharing a sentence is not in itself a finding about the gene and the disease.
CASP4LP shares sentences with these, for which no sentence is quoted: tumor (1 paper).